CHRFAM7A (CHRNA7 (exons 5-10) and FAM7A (exons A-E) fusion)
Synonyms: D-10; CHRNA7-DR1; CHRNA7
Tractability: Small molecule: a structure with a bound ligand is known; it belongs to a druggable protein family. Antibody: UniProt predicts a signal peptide or a membrane-spanning region; its Gene Ontology location is reachable by antibodies, with medium confidence.
Gene: Protein-coding gene on chromosome 15 (30,360,566 to 30,393,858, reverse strand). Ensembl gene ENSG00000166664.
Subcellular location: Membrane
Gene Ontology:
Molecular function: acetylcholine-gated monoatomic cation-selective channel activity; neurotransmitter receptor activity; extracellular ligand-gated monoatomic ion channel activity; monoatomic ion channel activity; transmembrane signaling receptor activity
Biological process: calcium ion transport; monoatomic ion transmembrane transport; regulation of membrane potential; synaptic transmission, cholinergic; chemical synaptic transmission, postsynaptic; cognition; excitatory postsynaptic potential; monoatomic ion transport; regulation of postsynaptic membrane potential
Cellular component: acetylcholine-gated channel complex; neuron projection; plasma membrane; synapse; membrane; postsynaptic membrane
Genetic constraint (gnomAD): Loss-of-function variants: 3 observed, 11.13 expected, observed/expected ratio (o/e) 0.27, 90% interval 0.12 to 0.7. The synonymous counts are far from expectation, so gnomAD's model fits this gene poorly and the ratio says little. Missense variants: 19 observed, 116.72 expected, observed/expected ratio (o/e) 0.16, 90% interval 0.11 to 0.24. Synonymous variants: 6 observed, 34.31 expected, observed/expected ratio (o/e) 0.17, 90% interval 0.095 to 0.34.
Homologues: Orthologues: chimpanzee CHRNA7 (95% identical), macaque CHRNA7 (94% identical), dog CHRNA7 (92% identical), rat Chrna7 (89% identical), mouse Chrna7 (89% identical), tropical clawed frog chrna7 (82% identical), zebrafish chrna7a (75% identical). Paralogues in human: CHRNA7 (95% identical), CHRNA4 (37% identical), CHRNA2 (36% identical), CHRNA10 (35% identical), CHRNA3 (34% identical), CHRNA9 (33% identical), CHRNB2 (32% identical), CHRNB4 (32% identical), CHRNA6 (32% identical), CHRNA1 (31% identical), CHRNB1 (31% identical), CHRNB3 (30% identical), and 33 more.
Diseases named in the same sentence as CHRFAM7A in open-access papers:
CHRFAM7A is named in the same sentence as 44 diseases in open-access papers, as found by Europe PMC text mining. Sharing a sentence is not in itself a finding about the gene and the disease. The quoted sentences say what the papers report.
schizophrenia (14 papers, 2007 to 2024). A major psychotic disorder characterized by abnormalities in the perception or expression of reality. "CHRFAM7A, a uniquely human fusion gene, has been associated with neuropsychiatric disorders including Alzheimer’s disease, schizophrenia, anxiety, and attention deficit disorder." (PMID 38711941, 2024). "Although no clinicalsignificance has yet been reported for this variant, CHRFAM7A hasbeen widely associated with neurological disorders such as schizophrenia and bipolardisorder." (PMID 38259032, 2024). "The patient's mother had a chromosome 15 duplication of the CHRFAM7A gene, which is also associated with schizophrenia and modulates α7* nicotinic receptor activity." (PMID 22214315, 2012). "Several studies have investigated whether the Δ2bp allelic variant of CHRFAM7A could confer susceptibility to schizophrenia." (PMID 35408823, 2022). "Finally, CNVs occur in the CHRNA7 and in CHRFAM7A, and deletions were strongly associated with schizophrenia." (PMID 26979166, 2016). "In addition, similarly high transcript levels were detected for the truncated dupα7 subunit transcript, encoded by the partially duplicated gene CHRFAM7A, which has been associated with psychiatric disorders such as schizophrenia." (PMID 25906356, 2015). "Pairwise analyses before and after antipsychotic treatment revealed an increase in CHRFAM7A gene expression during follow-ups compared to the baseline, thus suggesting that CHRFAM7A has a role in schizophrenia pathogenesis and treatment." (PMID 35408823, 2022). "Kunii and coworkers have observed that CHRFAM7A was upregulated in the brains of patients with schizophrenia and bipolar disorder, and the ratio of CHRFAM7A/CHRNA7 increased." (PMID 34067314, 2021). "The CHRFAM7A gene is a chimeric product of the CHRNA7 gene, which is genetically linked to multiple disorders with cognitive deficits, including schizophrenia and bipolar disorder." (PMID 33510659, 2020). "CHRFAM7A, like CHRNA7, is polymorphic, and variants in this gene were associated with auditory pathology in cases of schizophrenia." (PMID 32640505, 2020). "The same genetic polymorphisms, copy number variations and alteration in the pseudo-gene CHRFAM7A, which are presumed to diminish the functionality of the nAChR α7 receptor in schizophrenia, have also been detected in bipolar disorder." (PMID 26979166, 2016). "Deletions involving CHRNA7 are rare but are strongly associated with schizophrenia: these patients only have one copy of CHRNA7 and two copies of CHRFAM7A, leading to an altered CHRNA7/CHRFAM7A ratio, whereas 15q13.3 duplication has been linked to childhood-onset schizophrenia." (PMID 35408823, 2022). "In addition to the gene encoding the nAChR α7 subunit (CHRNA7) a partially duplicated variant (CHRFAM7A) has been identified in the human genome and both of these genes (CHRNA7 and CHRFAM7A) have been linked to schizophrenia." (PMID 25906356, 2015). "A reduced CHRNA7:CHRFAM7A ratio, due to increased CHRFAM7A and/or reduced CHRNA7 expression, has been reported in the prefrontal cortex of patients with bipolar disorder and schizophrenia." (PMID 35408823, 2022). "We have analysed more than 1,000 samples from schizophrenia, bipolar, epilepsy, and control white Caucasian patients and have found no example of CHRFAM7A duplication." (PMID 17573966, 2007).
Alzheimer disease (5 papers, 2022 to 2025). A progressive, neurodegenerative disease characterized by loss of function and death of nerve cells in several areas of the brain leading to loss of cognitive function such as memory and language. "Four DMRs in Braak III vs. Braak 0 fell within dark regions of Alzheimer's disease risk genes (ABACA7, AMY1A, CHRFAM7A, CR1)." (PMID 41235755, 2025). "Fibroblasts were reprogrammed from two subjects affected by Alzheimer’s Disease (AD), carrying respectively 0 (ancestral haplotype) and 1 copy of the CHRFAM7A gene (UB068-0 copy, UB052-1 copy)." (PMID 36684422, 2022).
COVID-19 (3 papers, 2021 to 2023). A disease caused by infection with severe acute respiratory syndrome coronavirus 2. "In injury and infection situations such as COVID-19, brain ischemia and skin burn, the downregulation of CHRFAM7A expression is associated with a worse prognosis." (PMID 36831101, 2023). "COVID-19-induced hypercytokinemia is associated with decreased expression of the pro-inflammatory dominant negative duplicate CHRFAM7A." (PMID 34088975, 2021). "We found that CHRFAM7A expression was decreased in COVID-19 patients, whereas most controls expressed the dominant negative CHRFAM7A duplicate." (PMID 34088975, 2021). "In conclusion, COVID-19-related hypercytokinemia shows some correlations with regulation of the Ach/α7nAChR pathway characterized by a decreased expression of the pro-inflammatory dominant negative duplicate CHRFAM7A." (PMID 34088975, 2021). "Expression of CHRFAM7A was significantly lower in critical COVID-19 patients compared to controls." (PMID 34088975, 2021). "IL6 mRNA and protein expression did not correlate with CHRFAM7A mRNA expression in both COVID-19 and HC (data not shown)." (PMID 34088975, 2021). "While clinical trials investigating the efficacy of vagus nerve stimulation or nicotine administration in COVID-19 for cholinergic anti-inflammatory pathway activation are ongoing, the impact of the expression of the dominant negative duplicate CHRFAM7A has never been considered." (PMID 34088975, 2021).
inflammatory bowel disease (3 papers, 2016 to 2023). A spectrum of small and large bowel inflammatory diseases of unknown etiology. "If so, it raises the possibility that CHRFAM7A expression in peripheral tissues could be associated with human inflammatory disease like, for example, inflammatory bowel disease (IBDs)." (PMID 27051591, 2016). "Although many changes in the expression of CHRFAM7A in inflammatory bowel disease and Crohn's disease have been documented, little is known about the role of CHRFAM7A in renal injury." (PMID 36479618, 2023). "A similar conclusion was drawn by Baird and colleagues, who showed that CHRFAM7A expression was increased, and that CHRNA7 expression was decreased in Inflammatory Bowel Disease (IBD), thus suggesting that CHRFAM7A may be an unrecognized target for the development of therapeutics for IBD." (PMID 35408823, 2022).
Crohn disease (2 papers, 2016 to 2023). A gastrointestinal disorder characterized by chronic inflammation involving all layers of the intestinal wall, noncaseating granulomas affecting the intestinal wall and regional lymph nodes, and transmural fibrosis. "Biopsies of Crohn's disease (N = 31), however, showed only small changes in CHRFAM7A expression (p < 0.04) and no change in CHRNA7." (PMID 27051591, 2016).
epilepsy (2 papers, 2007 to 2022). A brain disorder characterized by episodes of abnormally increased neuronal discharge resulting in transient episodes of sensory or motor neurological dysfunction, or psychic dysfunction. "The impact of CHRFAM7A gene expression and the presence of the Δ2bp polymorphism has also been evaluated in several neurological disorders, including in epilepsy and autism spectrum disorders (ASD)." (PMID 35408823, 2022).
osteoarthritis (2 papers, 2023 to 2024). A noninflammatory degenerative joint disease occurring chiefly in older persons, characterized by degeneration of the articular cartilage, hypertrophy of bone at the margins and changes in the synovial membrane. "Recently, CHRFAM7A was found to contribute to exacerbating inflammation and tissue damage associated with osteoarthritis, and thus being a novel genetic risk factor and therapeutic target for pain." (PMID 39526039, 2024).
cognitive decline (1 paper, 2024). "Informed by the underlying cell biology of CHRFAM7A, the association between visual spatial function and cognitive decline could be driven by a more resilient neuronal structure measured by the visual spatial relative strength, latently detecting CHRFAM7A direct allele carriers." (PMID 38711941, 2024).
fibrosis (1 paper, 2023). the formation of excess fibrous connective tissue in an organ or tissue in a reparative or reactive process. "Specifically, H&E and Masson's trichrome staining revealed less injury‐induced renal interstitial oedema and deceased fibrosis in CHRFAM7A overexpression transgenic mice compared to WT mice." (PMID 36479618, 2023).
lung disease (1 paper, 2025). "The remaining 11 genes in the region encode proteins associated with neurologic disorders (APBA2, CHRFAM7A, MTMR10, FAN1), skin and eye pigmentation or development (OCA2, HERC2, TJP1, TRPM1), nephritis (ARHGAP11B, MTMR10, FAN1), and lung disease (ENTREP2, NSMCE3)." (PMID 40013929, 2025).
psychosis (1 paper, 2007). "The polymorphism for the presence or absence of CHRFAM7A that we found to be associated with psychosis could theoretically be caused by BP3/BP4 deletions involving interrupted direct repeats defined by segments RQL." (PMID 17573966, 2007).
renal fibrosis (1 paper, 2023). A final common manifestation of a wide variety of chronic kidney diseases characterized by glomerulosclerosis and tubulointerstitial fibrosis. "Therefore, the aim of our study was to explore the effect of CHRFAM7A expression on renal fibrosis and inflammation, as well as its involvement in underlying mechanisms of renal damage." (PMID 36479618, 2023). "To explore the effect of human‐specific CHRFAM7A expression, an inflammation‐related gene, on renal fibrosis during obstructive nephropathy, we studied CHRFAM7A transgenic mice and wild type mice that underwent unilateral ureteral obstruction (UUO) injury." (PMID 36479618, 2023). "In summary, our experimental results show that the human‐specific CHRFAM7A gene can reduce renal fibrosis in mice with obstructive nephropathy by down‐regulating the TGF‐β1/Smad2/3 signalling pathway as well as inhibiting the release of inflammatory factors." (PMID 36479618, 2023). "Transgenic overexpression of CHRFAM7A gene inhibited UUO‐induced renal fibrosis, which was demonstrated by decreased fibrotic gene expression and collagen deposition." (PMID 36479618, 2023). "Next, in order to explore mechanisms by which CHRFAM7A expression can alleviate UUO‐induced renal fibrosis, we determined mRNA and protein expression of TGF‐β1 and Smad2/3 in kidneys from each group." (PMID 36479618, 2023). "Collectively, our findings demonstrate that overexpression of the human‐specific CHRFAM7A gene can reduce UUO‐induced renal fibrosis by inhibiting TGF‐β1/Smad2/3 signalling pathway to reduce inflammatory reactions and EMT of renal tubular epithelial cells." (PMID 36479618, 2023). "To determine the effects of the human specific CHRFAM7A gene on the development of renal fibrosis following UUO in mice, we examined morphological changes in kidney tissue and collagen deposition by staining paraffin sections with Masson's trichrome." (PMID 36479618, 2023). "Together, our data show that the human‐specific CHRFAM7A gene may be able to down‐regulate the TGF‐β1/Smad2/3 signalling pathway in the kidney, delaying the progression of renal fibrosis caused by obstructive injury." (PMID 36479618, 2023). "Our data imply that CHRFAM7A expression may alleviate renal fibrosis in UUO mice through inhibiting the TGF‐β1/Smad2/3 signalling pathway." (PMID 36479618, 2023). "Our findings suggested that the overexpression of the human‐specific CHRFAM7A gene can inhibit TGF‐β1‐induced EMT in HK‐2 cells and TGF‐β1/Smad2/3 signal axis, thus, reduce renal fibrosis that develops in response to obstructive nephropathy." (PMID 36479618, 2023).
Stroke (1 paper, 2024). Sudden impairment of blood flow to a part of the brain due to occlusion or rupture of an artery to the brain. "Cognitive reserve has been implicated in brain aging and susceptibility to disease thus considering CHRFAM7A genotype may facilitate risk stratification and identify new targetable mechanisms for neurodegeneration, neuroinflammation and stroke." (PMID 38711941, 2024).
type 2 diabetes (1 paper, 2023). "Thus, the aim of this work is to identify the effects of different types of exercises on the expression of the CHRNA7, CHRFAM7A and tumor necrosis factor-α (TNF-α) in leukocytes of healthy normal weight (HNW), and overweight with type 2 diabetes (OT2D) individuals." (PMID 36831101, 2023).
ulcerative colitis (1 paper, 2016). An inflammatory bowel disease involving the mucosal surface of the large intestine and rectum. "Colon biopsies of ulcerative colitis (N = 33) confirmed increased expression of CHRFAM7A and decreased in CHRNA7 expression (p < 0.001)." (PMID 27051591, 2016).
neurological disorders (3 papers, 2022 to 2025). "Many questions are still pending; in particular, the use of the CHRFAM7A expression level, which can be measured via blood samples, as a prognostic marker even in neurological disorders, or as therapeutic target, but whether to reduce or increase its expression, remains to be elucidated." (PMID 35408823, 2022).
psychiatric disorder (2 papers, 2013 to 2015). A disorder characterized by behavioral and/or psychological abnormalities, often accompanied by physical symptoms. "The CHRFAM7A and CHRNA7 genes that reside in the BP4–BP5 region have been linked to psychiatric disorders." (PMID 23320815, 2013).
tumor (2 papers, 2016 to 2017). "In both tumor types studied here, CHRFAM7A expression was significantly lower than in the paired non-tumor lung specimens." (PMID 28978081, 2017). "Interestingly, in addition to CHRNA7, only a few other nAChR subunit genes modified their expression due to the effect of tobacco (CHRFAM7A, CHRNA5, CHRNA9) or to the degree of tumor differentiation (CHRNA5), but these changes only happen in SQC-L tumors." (PMID 28978081, 2017).
immune disorders (1 paper, 2025). "Even if the exact role of dupα7 in immune cells is still not completely understood, the CHRFAM7A gene is only expressed by humans and has been implicated in various neurological and immune disorders." (PMID 41221292, 2025).
CHRFAM7A also shares sentences with these, for which no sentence is quoted: bipolar disorder (6 papers); infection (3); cognitive deficits (2); lymphopenia (2); Anxiety (1); autosomal dominant nocturnal frontal lobe epilepsy (1); bladder cancer (1); brain ischemia (1); childhood-onset schizophrenia (1); cognitive disorder (1); colitis (1); colon cancer (1); dementia with Lewy bodies (1); hypophosphatasia (1); injury (1); kidney stones (1); lung carcinoma (1); malaria (1); nephritis (1); nephrocalcinosis (1); nicotine dependence (1); periarthritis (1); Pick disease (1); Ureteral obstruction (1); viral infection (1).